OXCT1 (3-oxoacid CoA-transferase 1)
Diseases named in the same sentence as OXCT1 in open-access papers (continued):
Sharing a sentence is not in itself a finding about the gene and the disease.
colorectal cancer (1 paper, 2026). A primary or metastatic malignant neoplasm that affects the colon or rectum. "To investigate the regulatory mechanisms of OXCT1 expression in colorectal cancer, we performed a comprehensive screening using bioinformatics approaches." (PMID 41492470, 2026). "To address this discrepancy, we sought to confirm the potential role of OXCT1 in the liver metastasis of colorectal cancer." (PMID 41492470, 2026). "A Venn diagram visualization highlights the intersection, featuring the OXCT1 gene, which is downregulated in colorectal cancer within the datasets and exhibits a hazard ratio (HR) less than 1, suggesting a potential protective role." (PMID 41492470, 2026). "Collectively, these results indicate that YY1 is a key transcription factor of OXCT1 in colorectal cancer." (PMID 41492470, 2026). "In our study, we found that in CRC, OXCT1 regulated CDK8 expression by inhibiting the histone acetylation in colorectal cancer cells." (PMID 41492470, 2026). "We also assessed the relationship between the expression level of OXCT1 and colorectal cancer prognosis." (PMID 41492470, 2026). "We conducted overexpression and knockout experiments of OXCT1 in colorectal cancer cells." (PMID 41492470, 2026). "Results showed that OXCT1 overexpression significantly inhibited CRC metastasis, suggesting that OXCT1 might serve as a protective factor against colorectal cancer." (PMID 41492470, 2026).
keloid (1 paper, 2025). An irregularly shaped, elevated mark on the skin caused by deposits of excessive amounts of collagen during wound healing. "By analyzing public RNA-Seq data of keloid-derived fibroblasts, we were able to identify a significant fold change in expression of OXCT1 and BDH1 in keloid-derived fibroblasts, which was consistently manifested in the whole transcriptome data for BLM-treated skin in mice." (PMID 41161389, 2025).
mastitis (1 paper, 2019). Inflammation of breast tissue during lactation or postpartum due to an obstructed duct or infection. "For example, 3-oxoacid CoA transferase 1 (OXCT1) has been associated favourably with both milk production and mastitis resistance, and has been suggested to regulate mammary gland metabolism and milk synthesis during mastitis infection." (PMID 31765378, 2019).
meningioma (1 paper, 2019). A generally slow growing tumor attached to the dura mater. "Of note, the NF2—OXCT1 fusions all occurred in meningiomas that progressed to higher grade or were secondary to progression." (PMID 31039818, 2019).
metastatic colorectal cancer (1 paper, 2021). "OXCT1, which encodes a 3-oxoacid CoA transferase 1 enzyme necessary for ketone catabolism and then involving in the tricarboxylic acid cycle, was also expressed at higher levels in metastatic colorectal cancer cell lines." (PMID 34550275, 2021).
Myocardial fibrosis (1 paper, 2025). "Reduction in activity of BDH1 and OXCT1 leads to exacerbation of myocardial fibrosis resulting from oxidative damage." (PMID 41161389, 2025).
Obesity (1 paper, 2025). Accumulation of substantial excess body fat. "In contrast, intestinal Hmgcs2 was strongly induced in both WT and DIO mice, with Oxct1 upregulated only in obesity, indicating local ketone production and consumption." (PMID 41156456, 2025).
ovarian carcinoma (1 paper, 2019). A malignant neoplasm originating from the surface ovarian epithelium. "Among 26 genes that were differentially expressed and methylated between cisplatin-resistant and -sensitive ovarian cancer cells, 3-oxoacid CoA transferase 1 (OXCT1) was selected for further investigations." (PMID 35582723, 2019). "Notably, overexpression of OXCT1 conferred sensitivity to cisplatin in the ovarian cancer cells." (PMID 35582723, 2019).
tumor (33 papers, 2007 to 2026). "Blocking OXCT1 in β-cateninS33Y-mutated HCC abolished resistance to ketogenic therapy and reduced tumor glutamate levels." (PMID 41803092, 2026). "Both in vitro and in vivo experiments have indicated that the downregulation of OXCT1 significantly enhanced tumor migration and metastasis, suggesting a potential tumor-suppressive role for OXCT1 in the progression of CRLM." (PMID 41492470, 2026). "To unravel the mechanisms by which OXCT1 inhibits tumor metastasis, we performed transcriptomic sequencing analysis on HCT116-derived cell lines to find differentially expressed genes (DEGs) between AdGFP and AdOXCT1 groups." (PMID 41492470, 2026). "OXCT1 expression was increased in MYCN amplified tumours when compared to MYCN non‐amplified tumours in Asgharzadeh and Cangelosi datasets (*p < 0.05)." (PMID 41420301, 2025). "Consistently, the knockdown of OXCT1 by adenoviral injection in vivo can induce simultaneously skin fibrogenesis and aggravated fibrosis in skin treated with BLM." (PMID 41161389, 2025). "Accumulating evidence indicates that OXCT1 is dysregulated in various cancers, where it functions as an oncogene, driving tumor progression by modulating proliferation, metastasis, apoptosis, autophagy, and drug resistance." (PMID 41594546, 2025). "Highly expressed in TAMs, OXCT1 facilitates their polarization towards a pro-tumor phenotype through the succinate-H3K4me3-Arg1 axis." (PMID 40764998, 2025). "Taken together, these results demonstrate that dysfunction of ketone body metabolism induced by OXCT1 suppression induced a spontaneous onset of skin fibrogenesis and exacerbated BLM-induced fibrotic skin in mice." (PMID 41161389, 2025). "OXCT1, a key enzyme in ketone metabolism 39, was also highly expressed in tumor cells, suggesting its involvement in tumor immunity and treatment response." (PMID 40083932, 2025). "We found that OXCT1 expression negatively correlated with survival of patients with BCa, both in terms of tumor stage and response to therapeutic intervention." (PMID 39509334, 2024). "The mRNA expression of OXCT1 in tumor tissues was found to be significantly higher than that in normal tissues." (PMID 34804914, 2021). "Based on this analysis, we found that OXCT1 was highly expressed in tumor tissues and that its expression level was significantly negatively correlated with relapse-free survival (RFS)." (PMID 34804914, 2021). "These evidences prove that OXCT1 can help drive tumor progression and metastasis, and also confirm the reliability of our screening results." (PMID 34804914, 2021). "We reexamined the expression of BDH1 and OXCT1 in tumor tissues and found that these two genes were significantly upregulated." (PMID 29414764, 2018). "BDH1 and OXCT‐1 have been identified as potential neoplasm biomarkers; however, their mechanistic functions and therapeutic potentials in NB are unknown." (PMID 41420301, 2025). "Although we demonstrate that CD8+ T cells are required for the anti-tumour effects of DR, the Cd4-Cre model used in our study deletes Bdh1 and Oxct1 in both CD4+ and CD8+ T cell lineages; therefore, we cannot exclude a contribution of ketolysis in CD4+ T cells to the observed effects." (PMID 41366157, 2025). "OXCT1 affects tumor growth and gemcitabine sensitivity in mouse models." (PMID 39509334, 2024). "The main limitation of this study was the evaluation of other ketolytic enzymes including 3-hydroxybutyrate dehydrogenase 1(BDH1), 3-hydroxybutyrate dehydrogenase 2 (BDH2) and succinyl CoA: 3-oxoacid CoA transferase 1 (OXCT1) in the tumour and pre-tumour tissues of the OSCC patients." (PMID 36816175, 2023). "Tumor growth inhibition induced by GEM in vivo reduced after OXCT1 overexpression." (PMID 34804914, 2021). "Finally, we detected BDH1 and OXCT1 expression levels in tumor tissue by qRT-PCR and immunohistochemistry." (PMID 29414764, 2018).
tumor (continued). "The use of BDH1 and OXCT1 inhibitors may enhance KD treatment efficiency and expand the anti-tumor spectrum of KD therapy." (PMID 29414764, 2018). "Notably, we observed no corresponding upregulation of gene expression with one only exception Oxct1, consistent with the physical elimination of tumor vascular endothelial cells." (PMID 27498762, 2016). "Notably, the regulatory effect of OXCT1 on tumor cell migration could be reversed by a CDK8 inhibitor." (PMID 41492470, 2026). "Levels of both ketolytic and glycolytic genes were significantly higher in MYCN amplified tumours when compared to MYCN non‐amplified tumours, with the exception of OXCT‐1 in the Kocak dataset." (PMID 41420301, 2025). "Inhibition of OXCT1, either pharmacologically or through genetic knockout, reduces TAM-mediated immune suppression, enhances T cell cytotoxicity, and slows tumor progression." (PMID 40764998, 2025). "A study has shown that targeting 3-oxoacid CoA-transferase 1 (OXCT1) to regulate ketone body metabolism in macrophages helps to reduce the depletion of CD8+ T cells, which in turn maintains their anti-tumor function and enhances immune responses." (PMID 40006033, 2025). "The gene expression of ketolytic enzymes BDH1, OXCT1 and ACAT1 were analysed in the context of MYCN amplification, INSS tumour stage progression and overall event free survival." (PMID 41420301, 2025). "We performed western blot analysis to verify the expression level of OXCT1 in PDAC and transformed epithelial cell lines, primary tumor tissues, and paired adjacent normal pancreatic tissues." (PMID 34804914, 2021). "We also observed that KD treatment suppressed tumor growth in nude mice with xenografts derived from HeLa cells with downregulated BDH1 and OXCT1." (PMID 29414764, 2018). "The difference in mean tumor volume between mice with siR-BDH1-and-OXCT1 HeLa cell xenografts in the KD and STD groups at the third week was statistically significant (P < 0.01)." (PMID 29414764, 2018). "Conversely, OXCT1 and ACAT1 expression levels were decreased in INSS stage 4 tumours, when compared to stage 1 in all datasets, indicating the potential reduced reliance of metastatic NB on rate‐limiting ketolytic enzymes under nutrient stress, while BDH1 levels were unchanged." (PMID 41420301, 2025). "The glycolytic genes, HK2, GAPDH and ENO1, were chosen as they mediate early, mid and final stages of glycolysis respectively, and all three ketolytic genes BDH1, OXCT1 and ACAT1 were analysed for MYCN amplification, survivability and tumour stage progression in three NB datasets." (PMID 41420301, 2025). "Other genes annotated on chromosome 20 are involved in mammary gland metabolism (GHR, OXCT1), antibody production and phagocytosis of bacterial cells (C6, C7, C9, C1QTNF3), tumor suppression (DAB2), involution of mammary epithelium (OSMR) and cytokine regulation (PRLR)." (PMID 25658712, 2015). "Network 3 was characterised by the insertion of a hub protein HNF4alpha, a transcription factor recently shown to play a role in other neoplasias and Network 4 was characterised by numerous mitochondrial-localised proteins (CAT, IDH3A, NDUFS3 and other complex 1 proteins, OXCT1 and PRDX3)." (PMID 24838487, 2014).
cancer (23 papers, 2013 to 2026). A tumor composed of atypical neoplastic, often pleomorphic cells that invade other tissues. "The role of OXCT1 has been implicated in several cancers, included CRC, and OXCT1 was overexpressed in the metastatic CRC cell line CC-M3." (PMID 30155352, 2018). "OXCT1, also known as succinyl-CoA transferase (SCOT), exhibits varied expressions in different types of cancer." (PMID 39857793, 2025). "Here, we report a gemcitabine resistance mechanism that promotes cancer reprogramming via the metabolic enzyme OXCT1." (PMID 39509334, 2024). "Orthotopic mouse models of BCa supported OXCT1 as a mediator of gemcitabine sensitivity through ketone metabolism and regulating cancer stem cell differentiation." (PMID 39509334, 2024). "Studies have shown that the expression of OXCT1 is significantly increased in different types of cancer cells and provided great potential in cancer therapy." (PMID 37164974, 2023). "Presently, research on OXCT1 mainly focused on human cancers and ketoacidosis; however, its functional study in adipose tissue of domestic animals was limited." (PMID 36672778, 2022). "Despite interindividual variations, we found that the expression of OXCT1 was significantly higher in cancer tissues than in para-cancerous tissues." (PMID 34804914, 2021). "Here, we determined expression levels of genes encoding the ketolytic enzymes 3-hydroxybutyrate dehydrogenase 1 (BDH1) and succinyl-CoA: 3-oxoacid CoA transferase 1 (OXCT1) in 33 human cancer cell lines." (PMID 29414764, 2018). "Nevertheless, overall, our results suggest that expression of the key ketolytic enzymes BDH1 and OXCT1 is one of the main factors that determine the effect of a KD on cancer." (PMID 29414764, 2018). "Based on these and other ketone-related studies, it appears that the enzymes driving ketone re-utilization, namely ACAT1 and OXCT1, would be excellent therapeutic targets for drug development, especially for the eradication of cancer stem cells (CSCs)." (PMID 29108233, 2017). "So, effective ACAT1 and OXCT1 inhibitors would be expected to phenotypically drive ATP depletion in cancer cells." (PMID 29108233, 2017). "Notably, the expression of ECI2, MCCC2, SUCLG2, and CPT2 was higher and that of OXCT1 was lower in cancer tissues than in para‐cancer tissues." (PMID 39491527, 2024). "OXCT1, an enzyme that catalyzes the reversible transfer of CoA from succinyl-CoA to acetoacetate in mitochondrial membranes, is considered a therapeutic target in cancer by virtue of its regulation of ketone bodies." (PMID 34680521, 2021). "Expression levels of BDH1/2 and OXCT1/2 mRNAs in 33 cancer cell lines were determined by qRT-PCR." (PMID 29414764, 2018). "BDH1 and OXCT1 may be very useful biomarkers to determine the sensitivity of a particular cancer to a KD." (PMID 29414764, 2018). "We investigated BDH1/2 and OXCT1/2 expression in several cancer cell lines and tested this hypothesis with two representative cell lines that had low and high expression levels of these key ketone body catabolism enzymes in vivo and in vitro." (PMID 29414764, 2018). "The discovery of OXCT1 and OVOL1 as metabolic and transcriptional regulators of gemcitabine sensitivity has broader implications in other gemcitabine-treated cancer types." (PMID 39509334, 2024). "This is due to deficiencies in succinyl-CoA:3-ketoacid coenzyme A transferase (OXCT1/SCOT), 3-hydroxybutyrate dehydrogenase 1 (BDH1) and acetoacetyl-CoA thiolase in cancer cell mitochondria." (PMID 37233716, 2023). "We showed that xenograft tumors that derive from cancer cells with low expression levels of BDH1 and OXCT1 are more responsive to KD therapy, likely because they possess weaker ability to metabolize ketone bodies." (PMID 29414764, 2018). "In this report, we molecularly targeted OXCT1 and ACAT1, to prevent cancer cells from recycling ketone bodies into Acetyl-CoA, which normally enters the TCA cycle, driving mitochondrial ATP production." (PMID 29108233, 2017).
cancer (continued). "Our results suggest that cancer cells with very low expression levels of BDH1 and OXCT1 may be sensitive to KD therapy." (PMID 29414764, 2018). "Further studies are necessary to determine whether other tumors derived from cancer cells with different expression levels of BDH1 and OXCT1 exhibit similar sensitivity to KD." (PMID 29414764, 2018).
metabolic disorder (3 papers, 2013 to 2022). "OXCT1 deficiency also explains the ketosis seen in FRDA patients carrying BSCL2 variants when exposed to a high fat diet, and emphasizes the features of FRDA as a specific metabolic disorder in addition to being a disorder of mitochondrial function." (PMID 36016708, 2022).
cardiovascular disease (2 papers, 2017 to 2025). "OXCT1 encoding enzyme SCOT1 is essential for ketone body metabolism and involved in cardiovascular disease, which are shown to be strongly associated with the course of RA, suggesting this enzyme may potentially contribute to RA prognosis." (PMID 29340042, 2017). "Together, the reduction in OXCT1 and CALM3 observed in protein-restricted fetuses highlights an early metabolic and structural vulnerability that may predispose the heart to maladaptive remodeling and cardiovascular disease in later life." (PMID 41244074, 2025).
infection (2 papers, 2019 to 2023). The state of being infected such as from the introduction of a foreign agent such as serum, vaccine, antigenic substance or organism. "Metabolic attacks following infection, ketone positivity in blood and urine, and asymptomatic state between attacks all supported succinyl-CoA 3-ketoacid-CoA transferase (SCOT) deficiency, and the compound heterozygosity for the OXCT1 gene complied with the autosomal recessive inheritance." (PMID 37377599, 2023). "Furthermore, the expression of two of these genes (NUP35 and OXCT1) was enriched in immune tissues implying a potentially pleiotropic effect or likely role in milk production during udder infection, which needs to be further elucidated in future studies." (PMID 31765378, 2019).
OXCT1 also shares sentences with these, for which no sentence is quoted: glioblastoma (3 papers); brain tumor (2); depression (2); Ketoacidosis (2); neuroblastoma (2); pancreatic ductal adenocarcinoma (2); acute myocardial infarction (1); Anxiety (1); Atrophy (1); Chlamydial disease (1); chronic heart failure (1); COVID-19 (1); cystic kidneys (1); Encephalopathy (1); epilepsy (1); Hepatic fibrosis (1); hepatoblastoma (1); Infertility (1); ischemia (1); kidney damage (1); lentivirus infection (1); malnutrition (1); melanoma (1); metastatic prostate carcinoma (1); protein (1); psychomotor delay (1); Sepsis (1); type 1 diabetes mellitus (1); viral infection (1).